HIF1A (hypoxia inducible factor 1 subunit alpha)
Diseases named in the same sentence as HIF1A in open-access papers (continued):
Sharing a sentence is not in itself a finding about the gene and the disease.
tumor (continued). "We showed that the HIF-1α pathway has major effects on MM cells and demonstrated that EZN-2968 treatment can reverse the Warburg cell phenotype pushing tumor cells towards a normal cell metabolism." (PMID 24732040, 2014). "The correlation between HIF-1α or VEGF expression and the tumor microvessel density (MVD) was then determined." (PMID 25289039, 2014). "Hypoxia-induced miRs, such as Let-7 and miR103–104 are induced by HIF-1α and target argonaute 1, which in turn increases VEGF mRNA expression and tumor xenograft growth." (PMID 24914051, 2014). "The results demonstrated that HIF-1α, VEGF and CD34 were overexpressed in the 22 sacral GCTB specimens, and overexpression of HIF-1α and VEGF correlated with the tumor MVD." (PMID 25289039, 2014). "74% of tumours evaluated that had detectable HIF-1α, also had proline-hydroxylated HIF-1α (71% head and neck, 70% breast, 100% lung and 89% bladder)." (PMID 24563687, 2014). "Conversely, with increasing evidence that some reactions (such as increased HIF-1α) in the periablational rim may stimulate growth in distant tumor, successful modulation of local tissue reactions may assume increasing clinical relevance as its own endpoint separate from tumor growth." (PMID 25133740, 2014). "Because most GBM express EGFR and since HIF1α is a marker gene upregulated upon hypoxia in GBM, proscillaridin A likely influences GBM tumor growth via various mechanisms." (PMID 25400117, 2014). "The genetic silencing of HIF-1α expression reduced the IMQ-enhanced glucose utilization and sensitized tumor cells to IMQ-induced apoptosis." (PMID 24658058, 2014). "We found that HIF-1α proline-hydroxylated at both VHL binding sites (Pro402 and Pro564), was present in hypoxic regions of a wide range of tumours, tumour xenografts and in moderately hypoxic cells in vitro." (PMID 24563687, 2014). "HIF-1α-VEGF axis regulating angiogenesis program plays a critical role in ischemic tissue and tumor." (PMID 25984487, 2014). "Tumor tissue responded to thermal ablation with a decrease in SDF1 and HIF-1α proteins, and an increase in HSP27 and HSP70 proteins, and decreases in Lifr and Sele genes transcripts." (PMID 24270800, 2014). "At the protein level, ablation resulted in decreased levels of SDF1 and HIF-1α and increased levels of HSP27 and HSP70 in the surviving tumor." (PMID 24270800, 2014). "Pharmacological inhibition of HIF1α or the CXCL12/CXCR4 axis reduced BM-derived cell recruitment and prevented tumor recurrence." (PMID 25526031, 2014). "It has been recently reported that miR-21 overexpression in human prostate cancer cells increased hypoxia-inducible factor-1α (HIF-1α) and VEGF expression, thereby inducing tumor angiogenesis." (PMID 24356956, 2014). "Molecular studies done on excised tumor (A549) tissue suggested that BBR in SD form resulted in a significant decrease in the survivin, Bcl-2, cyclin D1, MMP-9, HIF-1α, VEGF and CD31 expressions." (PMID 24614362, 2014). "The combination of Endostar with radiotherapy was investigated and the results indicated that this combination significantly inhibited tumor cell proliferation and TGF-β1, HIF-1α and bFGF expression." (PMID 24669250, 2014). "Immunohistochemistry was used to detect GLUT-1, HIF-1α, PI3K, and p-Akt expression in paraffin wax-embedded tumor specimens." (PMID 24980293, 2014). "In contrast, HIF-1α can upregulate VEGF and GLUT1, making tumor cells resistant to apoptosis, so inhibition of HIF-1α would promote apoptosis." (PMID 25105148, 2014).
tumor (continued). "In turn, succinate inhibits the prolyl hydroxylase that primes HIF1α for proteasomal degradation, and HIF1α stabilization is required for tumorigenesis both in vitro and in xenografts of TRAP1-expressing tumor cells." (PMID 25564869, 2014). "Glut-1, HIF-1α, PI3K and phosphorylated-Akt (p-Akt) expression was detected by immunohistochemical staining of paraffin sections from the tumor specimens." (PMID 24944654, 2014). "Collectively, miR-338-3p inhibits HCC tumor growth and sensitizes HCC cells to sorafenib by down-regulating HIF-1α." (PMID 25531114, 2014). "Tissue analysis revealed a correlation of BAG3 with HIF-1α (r = 0.815, P = 0.000), and HIF-1α showed the same change with the level of BAG3 expression in most of the tumor tissue." (PMID 24895585, 2014). "Others have shown that hypoxia increases CXCR4 expression through HIF-1α activation and that HIF-1α enhances the expression and function of CXCR4 in normal cells monocytes, macrophages and endothelial cells and in tumor cells." (PMID 24629239, 2014). "The combination of two aspects results in the switch of HIF-1α/β to HIF-2α/β followed by the activation of different target genes, leading to the malignant behavior of tumor cells." (PMID 24316875, 2014). "To determine the relationship between the induction of HIF-1α and apoptosis in IMQ-treated tumor cells, we used HIF-1α siRNA to reduce HIF-1α expression and then determined the level of apoptosis in IMQ-treated cells." (PMID 24658058, 2014). "According to previous studies on DEC1 expression and hypoxia-inducible factor 1 alpha (HIF-1α), a high expression of DEC1 in tumor tissue was induced by hypoxia." (PMID 24758579, 2014). "Many of these responses are mediated through the HIF class of transcription factors, because both HIF-1α and HIF-2α can influence the expression of key target genes for tumor growth and progression." (PMID 25347326, 2014). "CO2 therapy significantly decreases expressions of both HIF-1α and VEGF in human MFH, which suggests that CO2 therapy reduces hypoxia in the treated tumor tissue." (PMID 24988190, 2014). "It is well acknowledged that hypoxia-conducive environment, resulting from the increasing distance between the growing tumor cells and the capillaries or from the inefficiency of new vessels, resulted in rapid up-regulation of VEGF and its receptor via HIF-1α." (PMID 24926985, 2014). "Along with HIF-1α, its downstream target, VEGF, plays a key role in tumor angiogenesis and is considered an attractive chemotherapeutic target." (PMID 25153728, 2014). "While CAIX expression alone has proven to be an unreliable independent marker of tumor hypoxia, the combined expression of CAIX and HIF-1α was significantly predictive of a worsened prognosis for HNSCC patients." (PMID 25127378, 2014). "Hypoxia inducible factor 1 alpha (HIF-1α) combines with HIF-1β, which is constitutively expressed, to form a dimer that can regulate a multitude of genes that result in tumor growth and progression." (PMID 24743777, 2014). "Recently, chemotherapeutic drug, doxorubicin, has been reported to induces HIF-1α accumulation, enhanced VEGF secretion and stimulated tumor angiogenesis in normoxic condition." (PMID 24658058, 2014). "Two HIFα subunits, HIF-1α and HIF-2α, are primarily responsible for regulating the tumor's adaptation to hypoxia." (PMID 24738058, 2014). "A positive correlation existed between the tumor-to-muscle ratio of 18F-FETNIM and the expression of each of these HIF-1α targets." (PMID 25215311, 2014).
tumor (continued). "Considering the relationship between CD133 and HIF-1α based on our study results, HIF-1α expression is increased with hypoxia, CD133 is expressed or retained in cancer cell cytoplasm, and tumor progression occurs as a result of this CSC-like function." (PMID 23558457, 2014). "Hypoxia-inducible factor-1 alpha (HIF-1α), one of the three homologues of the HIF alpha subunit (HIF-1α, HIF-2α, and HIF-3α), has been regarded as an important marker of tumor hypoxia." (PMID 25485635, 2014). "Inhibition of PTEN by miR-21 has been reported to induce tumor angiogenesis through Akt and ERK activation and HIF-1α expression." (PMID 24356956, 2014). "Many signals received from the tumor microenvironment can initiate EMT including TGFβ, hypoxia-inducible factor (HIF)-1α, EGF, WNTs, and Notch." (PMID 25566498, 2014). "Overexpression of miR-21 in DU145 cells increases the expression of HIF-1α and VEGF and promotes tumor angiogenesis." (PMID 25279461, 2014). "Our recent work indicates that tumor spheroids cultured on PDMS are hypoxic and they express HIF-1α and HIF-1β." (PMID 25343626, 2014). "The discovery of the hypoxia inducible factor-1 alpha (HIF-1α) and its role in tumour behaviour and treatment response has increased interest in the signal molecules related to tumour hypoxia." (PMID 24963348, 2014). "Second, IMQ induced ROS production, thereby increasing HIF-1α expression at the transcriptional and translational levels via the PI3K/Akt and STAT3 pathways, which triggered aerobic glycolysis in tumor cells." (PMID 24658058, 2014). "Similar to the signaling for IMQ-induced HIF-1α accumulation, we demonstrated that IMQ activated the PI3K/Akt and STAT3 pathways to enhance aerobic glycolysis in TLR7/8-negative tumor cells." (PMID 24658058, 2014). "The impaired PHD activity stabilizes HIF-1α under normoxic condition, which upregulates HIF target gene involved in cell growth stimulation and angiogenesis, thus contributing to tumor progression." (PMID 23888270, 2013). "HIF-1α expression were also correlated significantly to FIGO stage (P < 0.001), tumor cell type (P = 0.010), LN metastasis (P < 0.001)." (PMID 23927384, 2013). "Other studies have reported that HIF-1α upregulates VEGF and GLUT1 to make tumor cells resistant to apoptosis." (PMID 23426939, 2013). "EO771 tumors from mice pre-treated with NAC from day -7 were also similar to controls with regard to Hif-1α-positive cells (control n = 6; NAC n = 5; 5 sections stained and analyzed per tumor)." (PMID 23840457, 2013). "Our study links hTRM9L and tRNA modifications to inhibition of tumour growth via LIN9 and HIF1-α-dependent mechanisms." (PMID 23381944, 2013). "The expression of HIF-1α was detected in 87.76% (43/49) of the TSCC samples and in 33.33% (5/15) of the adjacent non-tumor tissues." (PMID 23251251, 2013). "Above all, HIF-1α and VEGF are major regulators of angiogenesis and of tumor progression in many types of cancer." (PMID 23326384, 2013). "Overexpression of HIF-1α and SNAI1 in HCC samples were shown to be correlated with pathological classification, TNM staging and tumor volume (P < 0.05)." (PMID 23496980, 2013). "A proportion of tumor cells displayed nuclear HIF-1α expression (5 day treated double arrows) and many HIF-1α positive infiltrating cells were seen in the tumor periphery (5 day treated, arrowheads)." (PMID 24403226, 2013). "Recent studies have revealed a tumour suppressive role of HIF-1α, probably due to HIF-1α-induced apoptosis or transactivation of specific genes that are targets for negative selection in human cancers." (PMID 23599780, 2013). "Recently the cardiac glycoside digoxin has been shown to inhibit HIF1α mRNA translation and PC3 tumor xenograft growth in mice." (PMID 23342109, 2013). "Inhibition of HIF1α, VEGF, and tumor vascularization by Bortezomib are additional benefits that accompany NFkB inhibition." (PMID 23408731, 2013).
tumor (continued). "Studies have demonstrated the correlation between HIF-1α and VEGF in tumor cells and solid tumors and high levels of HIF-1α expression appear to predict a poor prognosis for various types of cancer." (PMID 23251251, 2013). "RT-PCR revealed that the mRNA expression of HIF-1α and VEGF was present in the tumor tissues; however, it was barely detected in the corresponding adjacent normal tissues." (PMID 23251251, 2013). "Acriflavine, an antibacterial agent, binds to the PAS-B subdomain of HIF1α and HIF2α thereby preventing the binding to HIF1β, an effect that results in reduced VEGF production and tumor growth." (PMID 23408731, 2013). "Growth factors such as IGF1 and IGF2 drive HIF-1α through MEK1 and MEK2 signaling, that influences tumor glucolytic activity." (PMID 22875335, 2013). "Moreover, the anti-cancer effect of HIF-1α inhibitors is not limited to its direct activity on prostate cancer cells: in fact considerable evidence suggests that other stromal components, in primis immune cells, are influenced by hypoxic environment with consequences on tumour growth." (PMID 23551576, 2013). "Stabilizing the feedback of HIF-1α and MTDH, and activating PI3K would form a positive feedback loop to enhance tumor cells’ survive and the progression." (PMID 23984913, 2013). "Immunohistochemistry assay showed that the LDH-A, HIF-1α and Ki67 expression were all inhibited in EGC-treated tumor samples, while the apoptosis ratio was significantly elevated." (PMID 23457597, 2013). "The deactivated HIF-1α protein will reduce the production VEGF and thus inhibit tumour angiogenesis and thereby decrease cancer progression." (PMID 23690850, 2013). "The expression of HIF-1α, LDH-A and Ki67 were all down-regulated, while apoptosis ratio was elevated in EGC-treated tumor samples, implying that EGC also interrupted the HIF-1α/LDH-A pathway in vivo." (PMID 23457597, 2013). "The percentage of nuclear HIF-1α expression was higher in the BRCA1-2 carriers than in BRCAX cancers (p<0.05), and in all familial than in sporadic tumor tissues (p = 0.0045)." (PMID 23326384, 2013). "So far VEGF remains the most notable gene upregulated by HIF-1α and HIF-2α secondary to hypoxic stress in tumor microenvironment." (PMID 23673510, 2013). "Research showed that SU6668 played an important role in inhibiting proliferation and angiogenesis of tumor cells by down-regulating the expression of VEGFR2 and HIF-1α." (PMID 23984913, 2013). "The net effect of NO on tumor growth or apoptosis depends not only on its source and relative levels but also on the degree of activation of HIF1-α, heme oxygenase-1 (HO-1) and VEGF in the tumor microenvironment." (PMID 23964349, 2013). "The absence of these HIF1α-regulated hypoxia markers is in accordance with recent studies that show an inhibition of HIF1α expression induced by D-2HG and EGLN in IDH1-mutant tumor cells." (PMID 24252742, 2013). "HIF-1α preferentially induces glycolytic pathway, whereas HIF-2α regulates genes involved in tumor growth, cell cycle and maintaining stem cell pluripotency." (PMID 24324596, 2013). "HIF-1α and HIF-2α are usually detected to measure tumor oxygen levels because the HIF-1β subunit is constitutive." (PMID 24324596, 2013). "Combining DC101 with HIF-1α shRNA or metronomic Dox had a synergistic effect in suppressing growth of HT1080 xenografts, at least in part via induction of tumor endothelial cell apoptosis." (PMID 22684860, 2013). "Immunohistochemistry was used to detect GLUT-1, HIF-1α, PI3K, and p-Akt expression in paraffin-embedded tumor specimens." (PMID 24245510, 2013). "In the present study, it was proposed that the HIPK2-mediated inhibition of HIF-1α correlated with the suppression of MDR1 gene transcription and the sensitization of cobalt-treated tumor cells to adriamycin-induced apoptosis." (PMID 24137413, 2013). "HIF-1α and SNAI1 expression was detected in 65% (43/66) and 59% (39/66) of tumor samples, respectively." (PMID 23496980, 2013).
tumor (continued). "These cells were essential for tumor re-growth after the irradiation treatment by increasing the number of functional blood vessels in a HIF-1α and SDF-1-dependent manner, thereby increasing the tumor blood flow." (PMID 24213237, 2012). "This study correlated the presence of mTOR with the expression of HIF1α and VEGF, both of which are important for tumor angiogenesis." (PMID 23155381, 2012). "This drug is presumably believed to induce IH tumor regression through mechanisms similar to that noted in normal endothelial cells, and recent reports suggest that it may work in part through suppressing production of nitric oxide and HIF1α regulation of VEGF expression." (PMID 23170111, 2012). "More importantly, our previously published study using a mouse orthotopic model of human PC showed anti-tumor activity of CDF, which was consistent with inhibition of HIF-1α, VEGF, CSC signatures, miR-21, and miR-210." (PMID 23272057, 2012). "In our study, HIF1A, similarly to NOTCH1, correlated with most of the other tumor markers but less with MUC1 or NKX2-1 as markers of lung physiology." (PMID 23028920, 2012). "We also examined the effect of CDF treatment on the expression of miR-21 and miR-210, and the mRNA expression of HIF-1α, VEGF, and CSC signature markers in the tumor tissues." (PMID 23272057, 2012). "The tumor-suppressive function of VHL is best viewed in the context of its role as an E3 ubiquitin ligase that targets various substrates, including HIF-1α and atypical PKC." (PMID 22390300, 2012). "HIF-1α activates the transcription of multiple genes including VEGF-A, a key factor in tumor angiogenesis." (PMID 22616919, 2012). "CDF treatment decreased the relative mRNA levels of HIF-1α, VEGF, IL-6, CD44, and EpCAM in MiaPaCa-2 tumor sphere cells under hypoxic conditions." (PMID 23272057, 2012). "Although the expression of both HIF1α and HIF2α is similarly regulated by VHL, their roles in tumor development, tumor metabolism, and response to therapy are sometimes contrasted." (PMID 23178531, 2012). "HIF-1α has been shown to regulate transcription of VEGF and PEDF genes and the increased ratio of VEGF/PEDF is required for angiogenesis and tumor growth." (PMID 22952803, 2012). "An oxygen- and VHL/PHD-independent ubiquitination and proteasomal degradation of HIF-1α was observed after incubation of tumor cells with geldanamycin and the small molecule inhibitor NVP-AUY922 has been shown to reduce HIF-1α levels in human tumor xenografts." (PMID 22347438, 2012). "This pattern suggests inverse relation between SATB1 and HIF-1α co-expression and the co-expression of AR, ER, and BCL2 in the subgroup of HR-positive tumours." (PMID 22424533, 2012). "Ultimately, the HIF-1α-NIC heterodimer binds to the promoters of Notch targets and synergistically increases transcription of genes involved in tumor progression and angiogenesis." (PMID 23202921, 2012). "They conclude that miR-21 induces tumor angiogenesis through targeting PTEN, leading to activation of the AKT and ERK1/2 signaling pathways, and thereby enhancing HIF-1α and VEGF expression." (PMID 22295063, 2012). "Some of the HIF-1α positive tumors were also positive for HIF-2α and vice versa for HIF-2α expressing tumor." (PMID 22804960, 2012). "Expression analysis demonstrated that addition of bevacizumab under hypoxic conditions induced VEGF-A, GLUT-1 and HIF-1α in B16F10 cells as well as in UM cell lines and two of four primary UM tumor cultures." (PMID 23077404, 2012). "Hypoxia is the environmental factor best known for its ability to induce cancer metastasis; it also stabilizes HIF-1α and up-regulates the expression of VEGF, which, in turn, induces the formation of tumor-feeding vessels." (PMID 22390300, 2012). "Meanwhile, the expression of HIF-1α and VEGF were also down-regulated in apigenin-treated tumor samples." (PMID 22844340, 2012).